HGF (hepatocyte growth factor)
Diseases named in the same sentence as HGF in open-access papers (continued):
Sharing a sentence is not in itself a finding about the gene and the disease.
type 2 diabetes (24 papers, 2012 to 2025). "Previous studies have reported potential associations of higher serum HGF concentrations and increased type 2 diabetes risk." (PMID 27158627, 2015). "In marked contrast, however, HGF has also been implicated with a pathogenic role in macrovascular disease as HGF levels in type 2 diabetes patients correlated positively with carotid intimal-media thickness and plaque score." (PMID 25500583, 2014). "For example, delivering mRNA encoding hepatocyte growth factor (HGF) to β cells could provide an effective treatment strategy for type 1 or type 2 diabetes." (PMID 36706177, 2023). "It has also been proven that people with type 2 diabetes have particularly elevated HGF values when atherosclerotic changes are present, regardless of BP values." (PMID 39457546, 2024). "Higher concentrations of HGF have also been observed in patients with type 2 diabetes, especially those with AH." (PMID 39457546, 2024). "It is known that growth factors such as insulin, IGF-1 and HGF support beta cell growth and survival, but in people with type 2 diabetes the destructive effects of metabolic stress predominate and beta cell death or dysfunction occurs." (PMID 32978479, 2020). "Similar to what was observed with adipokines and myokines, HGF has uncertain mixed functions, which can improve the metabolic profile of type 2 diabetes or induce IR." (PMID 30214428, 2018). "Disruption of HGF and its receptor signaling enhanced pancreatic beta-cell death, and accelerated onset of Type 2 diabetes." (PMID 27158627, 2015). "Mendelian randomization and colocalisation estimates did not support evidence of causality between hepatocyte growth factor and type 2 diabetes-related cancers." (PMID 38290287, 2024). "The MESA results revealed that elevated levels of HGF predict incident type 2 diabetes." (PMID 30237882, 2018). "Overall these data highlight that the simultaneous presence of CHC and type 2 diabetes induces an evident increase of the following proinflammatory cytokines: IL-1α, IL-2R, IL-12, IL-18, CXCL9, MIF and HGF." (PMID 22745767, 2012). "The levels of MIF, insulin, ghrelin, leptin, glucagon, resistin and adipsin are similar in type 2 diabetes and CHD patients whereas IL-1α, IL-2R, IL-12, IL-18, HGF, and PAI-1 are higher in CHD patients than in type 2 diabetes patients (with p-value <0.01)." (PMID 22745767, 2012).
head and neck squamous cell carcinoma (23 papers, 2011 to 2025). A squamous cell carcinoma that arises from any of the following anatomic sites: lip and oral cavity, nasal cavity, paranasal sinuses, pharynx, larynx, and salivary glands. "HGF/c-MET signaling is involved in the metabolic reprogramming of tumor cells in head and neck squamous cell carcinoma regulating cell proliferation and invasion capabilities and affecting immune surveillance and activation in the tumor microenvironment." (PMID 40823073, 2025). "In head and neck squamous cell carcinoma, over half of the patients overexpress HGF which stimulates MET to induce the proliferation of cell cycle genes by activating STAT3 in the TME." (PMID 37727377, 2023). "The HGF-MET pathway plays a pivotal role in the progression of head and neck squamous cell carcinoma." (PMID 25633809, 2015). "In addition, fibroblasts can also elevate the glycolysis level of head and neck squamous cell carcinoma by secreting hepatocyte growth factor (HGF)." (PMID 39590360, 2024). "The hepatocyte growth factor receptor; also known as mesenchymal–epithelial transition factor (c-Met) and its ligand hepatocyte growth factor (HGF) are overexpressed in head and neck squamous cell carcinoma (HNSCC); and regulates tumor progression and response to therapy." (PMID 29231907, 2017). "HGF was found to be elevated in head and neck squamous cell carcinoma (HNSCC) patients compared to healthy individuals." (PMID 35069735, 2022). "However, studies have confirmed that the HGF/c-Met signaling pathway is abnormally activated in various types of cancer, such as lung cancer, breast cancer, gastric cancer, and head and neck squamous cell carcinoma (HNSCC), and is involved in the oncogenesis, invasion, and angiogenesis of tumors." (PMID 34970484, 2021). "Aberrant signaling of the hepatocyte growth factor (HGF)/c-Met pathway has been identified as a promoter of tumorigenesis in several tumor types including head and neck squamous cell carcinoma (HNSCC)." (PMID 28441771, 2017). "In a study on the head and neck squamous cell carcinomas (HNSCC), CAFs were observed to secrete large amounts of hepatocyte growth factor (HGF) under the influence of lactate produced by HNSCC cells." (PMID 34373744, 2021). "Functionally, head and neck squamous cell carcinoma (HNSCC) tumors have been reported to secrete growth factors, such as HGF and TGF-α, that act in an autocrine/juxtacrine fashion to upregulate JAG1 expression through the MAKP pathway." (PMID 25309874, 2014). "This review highlights three RTK signaling pathways involved in head and neck squamous cell carcinoma; EGFR, the type 1 insulin-like growth factor receptor (IGF-1R) and the hepatocyte growth factor (HGF) receptor (Met)." (PMID 21776391, 2011). "Examples of these include HGF inhibition, which reportedly reduces colon cancer tumor growth, potentially by reducing Wnt activity, and thereby CSC frequencies; or similarly, direct targeting of c-Met, the HGF receptor, that reduces CSC numbers in head and neck squamous cell carcinoma (HNSCC)." (PMID 27355964, 2016). "An aberrant HGF/c-MET signaling can lead to uncontrolled proliferation, motility, invasiveness, and angiogenesis and can play an essential role in the development, progression and survival of cancer including head and neck squamous cell carcinoma (HNSCC)." (PMID 35081970, 2022).
fibrosis (22 papers, 2013 to 2025). the formation of excess fibrous connective tissue in an organ or tissue in a reparative or reactive process. "Other studies have also indicated that HGF ameliorates lung injury and restores the integrity and permeability of endothelial cells in emphysema and fibrosis models." (PMID 37476061, 2023). "HGF alone combined with MSCs attenuated ischemic myocardial fibrosis, suggesting the importance of these growth factors expressed by PICs in cardiac repair and regeneration." (PMID 36552813, 2022). "Overexpression of the hepatocyte growth factor (HGF) in MSCs improved the recovery of hepatocytes in a fibrosis model." (PMID 34055744, 2021). "Our group previously reported several roles of HGF in damaged myocardium, including reduction of cardiac fibrosis and myocyte apoptosis, and enhancement of cytoskeletal protein expression." (PMID 30517097, 2018). "In summary, our results revealed that the infusion of human Ad-MSCs was beneficial in protecting lung tissue from radiation-induced fibrosis, and that this protection was largely the result of increased levels of endogenous HGF and PGE2 after Ad-MSC infusion." (PMID 25736907, 2015). "Fibrosis and impaired dysfunction of the kidneys during crizotinib therapy may be explained by blockade of the protective and anti-fibrotic activity of the HGF/c-Met pathway in the kidneys." (PMID 30257437, 2018). "HGF is known to have beneficial effect when administered in the bleomycin-induced fibrosis models." (PMID 25384638, 2014). "Furthermore, to elucidate the role of BMPC-derived HGF in regulating cardiac fibrosis, we inhibited HGF in mouse BMPC using siRNA and transplanted intramyocardially after MI in db/db mice." (PMID 23560074, 2013). "Based on our in vitro findings on alveolar epithelial wound repair, we studied HGF-modified BMSC in an in vivo bleomycin induced lung injury and fibrosis model." (PMID 23840329, 2013). "Although there is a report with the application using HGF gene therapy on a rat model of NAFLD-fibrosis, to the best of our knowledge, the therapeutic effect of recombinant HGF protein on the development of NASH has not been reported." (PMID 30083132, 2018).
squamous cell carcinoma (22 papers, 2004 to 2025). A carcinoma arising from squamous epithelial cells. "The role for HGF in VEGF production has been implicated in some cell types such as squamous cell carcinoma and synovial cells." (PMID 25332857, 2014). "Others have shown that HGF can stimulate release of the EGFR ligand amphiregulin in squamous cell carcinoma, a process dependent on the MAPK protein Erk2." (PMID 35325006, 2022). "Both the KHT and SCCVII squamous cell carcinoma secrete HGF and have elevated basal phosphorylation of Met, and as such, were predicted to be sensitive to c-Met inhibition." (PMID 30719213, 2019). "Overexpression of DS epimerase 1 in squamous cell carcinoma increases levels of DS chains in cancer tissue, which can mediate hepatocyte growth factor (HGF) signaling." (PMID 29864158, 2018). "HGF induced signalling efficiently confers this resistance in squamous cell carcinoma cells, with analysis of HGF-induced EGFR binding partners identifying direct interaction between EGFR and CDCP1." (PMID 26973855, 2016). "They significantly upregulate the secretion of hepatocyte growth factor, which promotes invasion of squamous cell carcinoma." (PMID 27843256, 2016). "HGF activation appears to contribute to the oncogenic potential of dysregulated matriptase in the development and progression of squamous cell carcinoma." (PMID 24705933, 2014). "Matriptase is an efficient activator of proHGF and dysregulated matriptase activity recently was shown to promote squamous cell carcinoma through activation of HGF-dependent c-Met signaling." (PMID 22952456, 2012). "Moreover, the presence of myofibroblasts, which are generated by tumor cell-derived TGF-ß and are predominantly present at the invasive margin, were shown to promote HGF-dependent invasion of the cancer cells in squamous carcinoma cells." (PMID 36868311, 2023). "Nakamura and colleagues have reported the expression of HGF inducers in several carcinoma cell lines, including squamous cell carcinoma, human epidermoid carcinoma, human non-small cell lung cancer cells, human cholangiocarcinoma cells, and SBC-3 human small cell lung carcinoma cells." (PMID 26013123, 2015). "Fibroblast-derived HGF/SF has been shown to stimulate invasion and migration in a number of tumour types including squamous cell carcinoma, and we have demonstrated previously that exogenous HGF/SF induces expression of the type IV collagenases MMP-2 and -9 in squamous carcinoma cells." (PMID 14970860, 2004). "Moreover, TGF-β negatively regulates c-MET and HGF mRNA levels in human squamous carcinoma cells." (PMID 29238047, 2017). "Within HN group, HGF/c-MET was detected in 7 of 17 (40%) squamous cell carcinomas (HN1, HN5, HN7, HN8, HN21, HN25, HN26), and 4 of 16 (25%) non-squamous cell carcinomas (HN12, HN15, HN16, HN33)." (PMID 21283737, 2011). "The OS rate was also higher in low HGF expression compared to high HGF expression of stromal fibroblasts in patients with squamous carcinoma and non-squamous carcinoma, respectively (p=0.003; p=0.032)." (PMID 27374174, 2016). "In the present study, the levels of α-smooth muscle actin (α-SMA), TGFβ1 and HGF were determined immunohistochemically in oesophageal precancerous lesions (low- and high-grade intraepithelial neoplasia; LGIEN and HGIEN, respectively), carcinoma in situ (CIS) and squamous cell carcinoma (SCC)." (PMID 24137336, 2013).
liver failure (21 papers, 2005 to 2025). A liver disease characterized by the liver losing or has lost all of its function. "Substantial activation of HGF/c-MET signaling is associated with hepatocyte proliferation and liver regeneration, and inhibition of these signaling pathways results in liver failure." (PMID 40325003, 2025). "In contrast, recombinant HGF appears to confer protection against liver failure by boosting liver regeneration in mice." (PMID 39363292, 2024). "MSCs are comparable to NAC against APAP-induced liver failure by secreting HGF with less regenerative retardation concerns, thus facilitating the application of MSCs in clinical therapy for APAP liver failure." (PMID 35246254, 2022). "In summary, MSCs exert anti-necrosis effects on APAP-injured hepatocytes to increase the survival of APAP-challenged mouse liver failure by secreting HGF, and the efficacy of transplanting MSCs is similar to those of the clinically used drug NAC." (PMID 35246254, 2022). "In accordance, serum HGF levels have been proposed as a prognostic marker for patients with liver failure." (PMID 34422825, 2021). "The WNT2 and HGF were also verified as targets of ID1 in resection‐induced liver failure in the mouse." (PMID 33635004, 2021). "On the contrary, recombinant HGF appears to confer protection against liver failure by boosting liver regeneration in mice and in humans." (PMID 34422825, 2021). "In hepatic failure and acute liver injury, increased blood HGF level plays an important functional role in liver regeneration but also induces expression of TGF-β family, which induces apoptosis during fibrogenesis and provides growth control in regeneration processes." (PMID 30405726, 2018). "HGF and IL-6 are important growth factor and cytokine of proliver regeneration after liver failure." (PMID 23251190, 2012). "Regeneration with recombinant HGF has been achieved in rodent models of liver failure." (PMID 16336649, 2005). "Moreover, in patients with liver failure the concentrations of HGF in the blood leaving the liver were higher than in the portal vein, which may indicate its synthesis in the setting of hepatic insufficiency." (PMID 26090463, 2015). "There have been well known reports of usage of liver failure sera and cholestatic sera upon hepatogenic induction of bone marrow stem cells, which describe the potential role of hepatogenic factors (including HGF) released from hepatocytes during liver damage or cholestasis." (PMID 24642599, 2014). "However, this severe adverse event was associated with progression of hepatic failure, not rh-HGF; no other severe adverse events directly caused by single or repeated doses of rh-HGF were observed during the study period." (PMID 21548996, 2011). "When HGF was knocked down, the protective effects of MSCs were reduced on APAP-induced hepatocyte necrosis and mouse liver failure." (PMID 35246254, 2022). "The other is that HGF, a hepatocyte growth stimulatory cytokine, is the major cytokine by which MSCs protect hepatocytes from APAP injury and rescue mice from APAP-induced liver failure." (PMID 35246254, 2022). "Results from early studies with native HGF/SF however are most encouraging because in a series of clinical trials involving a total of 5,902 patients who were administered natural HGF/SF for liver failure, no excess cancer mortality was reported." (PMID 35905995, 2022). "HGF, IGF1 and VEGFA play central roles in protecting against hepatic damage under hepatic I/R conditions and some of these growth factors are being tested in clinical trials, for instance on patients with liver failure." (PMID 34444713, 2021). "In liver transplant recipients (liver failure), we observed negative values of WE ratios for Il-6, HGF, and TGF-β (−0.1, −0.5, and −0.2, respectively)." (PMID 26090463, 2015). "As a result, 75% of septic mice were rescued by the HGF injections, while all control mice died of severe hepatic failure within 8 hours after septic challenge without HGF treatment." (PMID 22536224, 2012).
liver failure (continued). "Higher concentration of HGF in the hepatic vein and its strongly negative elimination ratio suggest that this growth factor may be intensively synthesized in the milieu of liver failure." (PMID 26090463, 2015). "Both of these symptoms were determined to accompany hepatic failure, but not rh-HGF dosing." (PMID 21548996, 2011). "In addition, transplantation of HGF-knockout mesenchymal stem cells reduced the survival rate of APAP-treated mice, and HGF administration increased the survival rate during APAP hepatotoxicity, indicating that HGF improved mouse liver failure induced by APAP administration." (PMID 39363292, 2024). "Studies have shown that HGF levels are higher in patients without liver failure, and the sera levels of VEGF, HGF, and IL-6 have been described as promising regeneration predictive markers in mice." (PMID 40304568, 2025). "The negative elimination ratios of Il-6, HGF, and TGF-β indicate the prevalence of their intrahepatic synthesis in liver failure." (PMID 26090463, 2015). "In conclusion, the differences in Il-6, TNF-α, HGF, and TGF-β observed in liver donors between the portal and hepatic veins seem to result from their removal by healthy liver, which is absent in liver graft recipients with hepatic insufficiency." (PMID 26090463, 2015).